NDRG2 (NDRG family member 2)
Diseases named in the same sentence as NDRG2 in open-access papers (continued):
Sharing a sentence is not in itself a finding about the gene and the disease.
tumor (continued). "The Ndrg2 promoter were frequently hypermethylated in tumor tissues in contrast to the PCHNT tissues of the same individual." (PMID 25823664, 2015). "Down-regulation of Ndrg1 and Ndrg2 have been reported in various cancer tissues, and have been regarded as tumor suppressors and/or metastasis suppressors." (PMID 25823664, 2015). "We also found that Ndrg2 down-expression is one of the affecting factors on tumor progression by multivariate analysis." (PMID 25823664, 2015). "As a result, the average tumor weight in mice injected with NDRG2-overexpressing HCT116 or HT-29 cells was significantly less than that of the control cells (P < 0.01)." (PMID 26317652, 2015). "Our previous research revealed that NDRG2, which was discovered by our research group, inhibited tumor cell proliferation and invasion." (PMID 26317652, 2015). "We found that the glucose uptake of tumour cells was inhibited significantly with increased Ad-NDRG2 compared with the Ad-LacZ group." (PMID 24636131, 2014). "The results of our study support the notion that NDRG2 plays an important role in tumour glucose metabolism, in which GLUT1 is a likely candidate contributor to glucose uptake suppression and tumour growth." (PMID 24636131, 2014). "Previous studies of NDRG2 function have included the following: anti-proliferation effects in tumor cells, differentiation into dendritic cells, and the induction of cell apoptosis." (PMID 25061501, 2014). "NDRG2 mRNA and protein levels have been shown to be down-regulated in a variety of human cancer cell lines and tumor tissues." (PMID 25061501, 2014). "Functions of Ndrg2 still remain to be elucidated but the gene has attracted particular attention because numerous studies have indicated that the NDRG2 protein is a tumor suppressor." (PMID 24816982, 2014). "N-myc downstream-regulated gene 2 (NDRG2), a novel tumour suppressor and cell stress-related gene, is involved in many cell metabolic processes, such as hormone, ion and fluid metabolism." (PMID 24636131, 2014). "The mice were killed at 21 days after the first intratumoural injection, and the tumours were removed for analysis of the glucose uptake and protein levels of NDRG2 and GLUT1." (PMID 24636131, 2014). "The newly identified tumor suppressor, N-myc downstream-regulated gene 2 (NDRG2), has been studied in various cancers because of its anticancer and antimetastasis effects." (PMID 25061501, 2014). "Accumulating evidence indicates that NDRG2 is a tumour suppressor gene that is downregulated or undetectable in many human cancers." (PMID 24636131, 2014). "In the past research, NDRG2 was shown as a tumor suppressor gene in many kinds of tumors, which promoted differentiation and apoptosis and inhibited proliferation in a variety of tumors." (PMID 23307246, 2013). "T24 cells infected with LEN-NDRG2 showed inhibition of proliferation both in vitro and in vivo, and NDRG2 overexpression can inhibit tumor growth and invasion in vitro." (PMID 24146910, 2013). "Protein level of NDRG2 from 30 pairs of normal and tumor specimens was also determined by western blot, and the results were consistent with that of RT-PCR analysis." (PMID 23307246, 2013). "The NDRG2 level was negatively correlated with tumor grade and pathologic stage(r=-0.248, p < 0.05), as well as increased c-myc level (r=-0.454, p< 0.001)." (PMID 24146910, 2013). "In this paper, our data suggest that in ESCC tissues, NDRG2 expression decreased progressively through tumour stages I to IV, and NDRG2 expression in the well-differentiated ESCC tissues was significantly high." (PMID 23800335, 2013).
tumor (continued). "The effects of NDRG2 overexpression on T24 cells and T24 nude mouse xenografts were measured via cell growth curves, tumor growth curves, flow cytometric analysis, western blot and Transwell assay." (PMID 24146910, 2013). "We also found that the expression of NDRG2 was inversely correlated with c-Myc, similar to that seen in other tumor cells." (PMID 24146910, 2013). "NDRG2 expression was positively correlated with depth of tumor invasion (P = 0.038), vascular invasion (P = 0.036), tumor grade (P = 0.039), and tumor size (P = 0.026)." (PMID 23307246, 2013). "N-Myc downstream-regulated gene 2 (NDRG2) is a candidate tumor suppressor gene, which plays an important role in controlling tumor growth." (PMID 24146910, 2013). "NDRG2, a member of N-Myc downstream regulated gene family, plays some roles in cellular stress, cell differentiation and tumor suppression." (PMID 22920753, 2012). "As a tumor suppressor, NDRG2 is inhibited to facilitate tumor development in the process of tumorigenesis." (PMID 22920753, 2012). "Considering NDRG2 has no influence on colony-forming ability and most kinds of chemotherapeutic drugs inhibit tumor growth through inducing apoptosis of cancer cells, the effect of NDRG2 on cisplatin-induced apoptosis was evaluated." (PMID 22920753, 2012). "Adhesion molecules involved in HCC metastasis were screened for possible contribution to NDRG2-mediated tumor inhibition." (PMID 21676268, 2011). "Significantly-reduced NDRG2 cytoplasmic staining was detected in tumor tissues compared to normal adjacent tissues." (PMID 21676268, 2011). "In this paper, we have examined the expression of NDRG2, a recently discovered gene with a proposed tumor suppressor activity, using a commercially available cancer profiling array covering 19 different human cancer forms." (PMID 21226903, 2011). "NDRG2 antagonizes transforming growth factor-β1 (TGF-β1)-mediated tumor cell invasion by down-regulating the expression of matrix metalloproteinase 2 (MMP2), plasminogen activator inhibitor type 1 (PAI-1) and Rho GTPase activity." (PMID 21676268, 2011). "From the Cancer Profiling Array, we saw that the level of NDRG2 mRNA was reduced by at least 2-fold in almost a third of the tumor samples, compared to the normal counterpart, and we observed a marked decreased level in colon, cervix, thyroid gland and testis." (PMID 21226903, 2011). "Using a two-tailed Mann-Whitney test revealed a significant reduction in NDRG2 mRNA levels in tumor tissue compared to the corresponding normal tissue (p = 0.02), albeit based on a small sample set." (PMID 21226903, 2011). "By labelling a human Cancer Profiling Array with a radioactive probe against NDRG2, we evaluated the level of NDRG2 mRNA in 154 paired normal and tumor samples encompassing 19 different human cancers." (PMID 21226903, 2011). "From the CPA results, we would also like to highlight tissues such as cervix and testis as candidate tissues with a potential decrease of NDRG2 mRNA between normal and tumor tissues." (PMID 21226903, 2011). "The mean values of NDRG2 mRNA expression level in primary carcinoma (tumour) cells were significantly lower vs. the of NDRG2 mRNA expression level in normal thyroid tissue (p < 0.0001)." (PMID 20804549, 2010). "The results of our study confirm also the reports of other authors, analysing the NDRG2 gene expression level in various neoplasms." (PMID 20804549, 2010). "It means that the decrease of the NDRG2 mRNA expression level in primary carcinoma (tumour) was accompanied by a fall in the NDRG2 mRNA expression level in metastases of the carcinoma to lymph nodes." (PMID 20804549, 2010). "A positive correlation was observed between NDRG2 mRNA expression in primary tumour cells and in the cancer metastases to lymph nodes (Rs = 0.7857; p < 0.05)." (PMID 20804549, 2010).
tumor (continued). "A comparison of NDRG2 gene expression in the two studied groups of patients with various degree of tumour progression, i.e., in Group pT1 and in Group pT2-pT4, did no show any statistically significant difference." (PMID 20804549, 2010). "The mean values of NDRG2 mRNA expression in the primary tumour tissues were statistically significantly lower vs. the levels of NDRG2 mRNA expression in macroscopically unchanged thyroid tissue (p < 0.0001)." (PMID 20804549, 2010). "A reduced NDRG2 gene expression has also been observed in a number of human neoplasms, which suggests its role as a suppressor gene of neoplasm." (PMID 20804549, 2010). "A positive correlation was observed between the NDRG2 mRNA expression level in primary carcinoma (tumour) cells and the NDRG2 mRNA expression in the same carcinoma metastases to lymph nodes (Rs = 0.7857; p < 0.05)." (PMID 20804549, 2010). "It has been proposed that NDRG2 is a candidate tumor suppressor gene since it induces apoptosis in certain cancer cells and mRNA was down-regulated or absent in several human cancers and cancer cell-lines." (PMID 20673333, 2010). "PRDX6 showed dense methylation only in IVD; NDRG2 showed a significant methylation in cell lines and in tumour tissue compared to normal tissue, suggesting a potential epigenetic regulation of the gene." (PMID 19257893, 2009). "Nevertheless, there was a trend towards NDRG2 methylation status with an advanced tumour stage of the CRC samples, with significant value detected in patients with AJCC stage IV (p < 0.05)." (PMID 19257893, 2009). "We were the first to identify human NDRG2 (AF 159092) and demonstrated that NDRG2 was a candidate tumor suppressor gene." (PMID 18940011, 2008). "NDRG2 mRNA was statistically significantly reduced in tumor compared to either normal tissue sample." (PMID 17935612, 2007). "Prompted by the finding that NDRG2 expression correlates inversely with tumor grade in various cancers, we set out to analyse NDRG2 mRNA expression during colorectal carcinogenesis in humans." (PMID 17935612, 2007). "There was a tendency for decreasing NDRG2 mRNA levels with increasing tumor stage according to Dukes' staging of the CRC samples, and this trend was found to be significant using linear regression (p < 0.05)." (PMID 17935612, 2007). "By calculating linear regression on the data, the result was a statistically significant linear trend (p < 0.05) for decreasing NDRG2 levels with increasing tumor stage." (PMID 17935612, 2007). "Notably, NDRG2-mediated ACC1 degradation significantly synergized with sorafenib to suppress tumor growth and angiogenesis." (PMID 41991725, 2026). "The overarching rationale was to create a multi-faceted epigenetic panel that captures different aspects of GBM biology: DNA repair and chemoresistance (MGMT), stress response and oncogenic signaling (NUPR1), tumor suppression (NDRG2), and developmental pathway activation (GLI1)." (PMID 41596413, 2026). "The contrasting methylation patterns of MGMT/NUPR1 and NDRG2/GLI1 in GBM may shed light on their opposing roles in tumor development and progression." (PMID 41596413, 2026). "NDRG2 was chosen as a putative tumor suppressor frequently epigenetically silenced in GBM." (PMID 41596413, 2026). "This study uncovered that metastatic tumor cells with a mesenchymal phenotype largely depend on glutamine utilization, with the gain of NDRG2 function using lentiviral expression abolishing the epithelial-mesenchymal transition and glutaminolysis in metastatic mucoepidermoid cancer (MC3) cells." (PMID 40378957, 2025). "Moreover, to seek the precise molecular mechanism of tumour development through the inactivation of NDRG2, we profiled phosphopeptides regulated by NDRG2/PP2A via 2-dimensional image converted analysis of liquid chromatography-mass spectrometry (2-DICAL)." (PMID 38474089, 2024).
tumor (continued). "We identify a novel vulnerability in ATL resulting from the relationship of the synthetic lethality between the loss of NDRG2 expression and cytoplasmic PRMT5/MEP50 activity and reveal a functional and promising therapeutic target for the treatment of NDRG2low tumours." (PMID 38474089, 2024). "Overexpression of SLC1A5 restores the attenuation of tumour metastasis by NDRG2." (PMID 37829798, 2023). "NDRG2 is a tumor suppress gene that inhibits cancer progression." (PMID 37507593, 2023). "The correlation between EHF and NDRG2 led us to hypothesize that EHF may function as a tumor suppressor in TNBC cells." (PMID 37958443, 2023). "Therefore, the upregulation of NDRG1 or downregulation of NDRG2 seemed to suppress tumor immunity, assist cancer cells to escape from immune elimination, and finally promote tumorigenesis." (PMID 35795037, 2022). "Loss of NDRG2 expression is a prognostic factor that correlates with TNM grade and tumor metastasis and has an inverse relationship with patient survival in various tumor patients." (PMID 36012631, 2022). "The expression of NDRG2 seems more reasonable to be suggested as a prognostic marker related to the reduction in pathological symptoms of the tumor rather than a diagnostic marker related to tumor development." (PMID 36012631, 2022). "Moreover, NDRG2 was negatively correlated with miR-181a-5p in tumor tissues (R2 = 0.443, P < 0.001)." (PMID 34951340, 2022). "Additionally, the functions of NDRG2 as a tumor suppressor contribute to tumor growth inhibition and anti-metastasis in various tumors." (PMID 36012631, 2022). "NDRG2 expressed in astrocytes of the central nervous system is negatively correlated with gpx8, which is involved in cell proliferation and differentiation and generally considered as a tumor suppressor." (PMID 36052280, 2022). "Furthermore, NDRG2 suppresses tumor invasion by attenuating matrix metalloproteinase 9 (MMP9) expression via NF-κB inhibition." (PMID 36012631, 2022). "By contrast, NDRG2 had lower expression in tumor tissues than in adjacent normal tissues." (PMID 34951340, 2022). "In this review, we summarize information on the clinicopathological characteristics of tumor patients according to NDRG2 expression in various tumor tissues and provide information on the metastasis inhibition-related cell signaling modulation by NDRG2." (PMID 36012631, 2022). "Although NDRG2 expression likely inhibits NF-κB-mediated tumor metastasis, how NDRG2 inhibits NF-κB activity remains unclear." (PMID 36012631, 2022). "Recent studies demonstrated that NDRG2 functions as a tumor suppressor and may be a prognostic predictor for many different malignant tumors." (PMID 34013046, 2021). "Therefore, this shows that NDRG2 expression regulates pro/antiapoptotic protein levels, increasing the sensitivity of tumor cells to anticancer drugs." (PMID 34685629, 2021). "The inhibition of TCF/β-catenin activity by NDRG2 suppresses tumor metastasis." (PMID 34685629, 2021). "Multiple reports have already demonstrated that NDRG2 expression in cancer cells is able to inhibit the NF-κB, MAPK, and STAT signaling pathways, thus raising the hypothesis that NDRG2 expression may hamper PD-L1 expression in tumor cells." (PMID 34885221, 2021). "Despite the accumulated evidence indicating a tumor suppressive role of NDRG2 in various types of tumors, the question of whether the interaction between tumor cells and immune cells can be influenced by NDRG2 expression in tumor cells remains unanswered." (PMID 34885221, 2021). "Additionally, NDRG2 is a substrate of novel death-associated protein kinase 1 (DAPK1), which promotes apoptosis induced by various stimuli and plays a role in tumor suppression." (PMID 34685629, 2021).
tumor (continued). "We investigated whether NDRG2 acted in a paracrine manner to regulate tumor angiogenesis using HepG2 and Hep3B cells." (PMID 34013046, 2021). "There are several reports that show that NDRG2 contributes to drug sensitivity in tumor cells." (PMID 34685629, 2021). "Collectively, our data support the hypothesis that NDRG2 plays a crucial role as a tumor suppressor via decreased expression of immune checkpoint molecules that are involved in antitumor immune responses." (PMID 34885221, 2021). "Blocking T cell proliferation by coculture with 4T1 mouse tumor cells that express high levels of PD-L1 could be significantly reversed by NDRG2 overexpression in the same tumor cells." (PMID 34885221, 2021). "NDRG2 is known as a tumor suppressor gene through inhibition of tumor growth and metastasis." (PMID 33007962, 2020). "Due to the tumor-suppressive function of NDRG2 via regulating EMT and metabolic reprogramming in multiple types of cancers 38, 39, we suppose the generation of metastatic tumor specific phenotype might be associated with NDRG2 downregulation in MC3 cells." (PMID 33162818, 2020). "NDRG2 which is a member of NDRG family is reported to act as a tumor suppressor gene." (PMID 32592365, 2020). "Furthermore, NDRG2 overexpression enhanced gemcitabine-mediated inhibition of tumor growth, suggesting the role of miR181c/NDRG2 signaling in modulating gemcitabine response in CCA." (PMID 33007962, 2020). "Low NDRG2 expression was related to some phenotypes of tumor aggressiveness, such as advanced clinical stage (OR = 3.21, 95% CI: 1.96–5.26, P < .001), positive lymph node metastasis (OR = 2.14, 95% CI: 1.49–3.07, P < .001), and poor degree of differentiation (OR = 0.60, 95% CI: 0.45–0.81, P = .001)." (PMID 33031336, 2020). "Xenograft tumor assay was performed to detect the in vivo function of NDRG2." (PMID 32345304, 2020). "NDRG2, as a tumor suppressor, mainly suppresses cancer development and progression." (PMID 31121982, 2019). "The tumor suppressor NDRG2 also plays an important role in tumor metabolic reprogramming." (PMID 31523182, 2019). "In addition, restoration of NDRG2 rescued the miR-130a-imposed impetus for tumor proliferation and metastasis." (PMID 30206227, 2018). "NDRG2 has long been regarded as a candidate tumor suppressor gene." (PMID 29445150, 2018). "In addition, HE staining of the lungs revealed that the tumor nodules originated from the NDRG2 knockdown cells presented serious tissue destruction and/or necrosis, whereas those derived from the control cells exhibited scattered tumor nodules." (PMID 30206227, 2018). "Moreover, previous studies have shown that NDRG2 mRNA expression is low in numerous types of tumor tissues and cancer cell lines, and is a novel tumor suppressor candidate gene." (PMID 28390436, 2017). "NDRG2 has been reported to modulate tumor-related genes; however, whether NDRG2 is a transcription factor itself or acts via other transcription factors is unclear." (PMID 26506239, 2016). "Thus, NDRG2 overexpression can suppress MMPs via various mechanisms, which further suppress tumor invasion." (PMID 26506239, 2016). "The NDRG2 level is negatively correlated with tumor grade and pathologic stage." (PMID 26506239, 2016). "The anti-tumor effects of NDRG2 are exerted via various mechanisms and pathways, and NDRG2 expression levels are regulated by numerous factors and treatments, which may provide insight into methods for successfully treating cancer." (PMID 26506239, 2016).